ADAM17 (ADAM metallopeptidase domain 17)
Diseases named in the same sentence as ADAM17 in open-access papers (continued):
Sharing a sentence is not in itself a finding about the gene and the disease.
Immunodeficiency (6 papers, 2020 to 2025). Failure of the immune system to protect the body adequately from infection, due to the absence or insufficiency of some component process or substance. "Whether these mechanisms promoting enhanced ADAM17 activity also lead to suppression of phagocytosis and potential immune deficiencies needs to be studied." (PMID 32825187, 2020). "Since ADAM17 has emerged as a protease that contributes to the pathogenesis of a multitude of disease states, a wide majority of small molecules synthesized so far as selective ADAM17 inhibitors were tested in tumors, chronic inflammatory diseases, and immune disorders." (PMID 39768182, 2024).
Myocardial fibrosis (6 papers, 2022 to 2025). "A homolog of ACE, ACE2, which is cleaved by ADAM17, reduces myocardial fibrosis, hypertrophy, and apoptosis by binding to the MAS receptor (MASR)." (PMID 40224489, 2025). "Our study found that ADAM17 inhibition combined with eplerenone significantly improved myocardial fibrosis, apoptosis, and inflammation in diabetic mice by dual inhibition of Ang II and aldosterone, without affecting blood potassium concentration." (PMID 38799171, 2024). "Our previous study found that dickkopf-3 (DKK3) overexpression adequately alleviated Ang II-induced myocardial fibrosis in mice through ADAM17/ACE2 pathway." (PMID 36313337, 2022). "Thus, cardiomyocyte-specific knockout of ADAM17 alleviated myocardial fibrosis and apoptosis in diabetic mice." (PMID 35909160, 2022). "In this study, we found that a high-glucose environment substantially increased the expression of TGF-β1; after knocking down ADAM17, the shearing of ACE2 decreased, and the TGF-β1 pathway was inhibited to reduce the degree of myocardial fibrosis." (PMID 38799171, 2024).
pancreatic ductal adenocarcinoma (6 papers, 2012 to 2025). An infiltrating adenocarcinoma that arises from the epithelial cells of the pancreas. "Previous studies have shown that ADAM17 is required for the development of pancreatic ductal adenocarcinoma (PDAC) in mice." (PMID 38069391, 2023). "Interestingly, ADAM17 is also upregulated in pancreatic tissues during pancreatitis, a precursor to pancreatic ductal adenocarcinoma (PDAC)." (PMID 40427200, 2025). "Similarly, silencing of ADAM17 expression decreased the invasiveness of pancreatic ductal adenocarcinoma cells as tested in vitro in matrigel-coated transwell system but did not influence their proliferation." (PMID 23251384, 2012). "Strikingly, ADAM17 and ERBB1/EGFR are both required to maintain high RAS activity in a KrasG12D mouse model of pancreatic ductal carcinoma." (PMID 35971826, 2022). "In pancreatic ductal adenocarcinoma (PDAC), ADAM17/TACE mRNA expression is upregulated in tumour-derived tissues and cell lines, and siRNA silencing of ADAM17 significantly reduced cancer cell invasion in lab-based models, although proliferation remained unaffected." (PMID 40427200, 2025). "While without stimulation ADAM10 was found at comparably high levels on all cell types analyzed, ADAM17 was almost not detectable on T cells and only present at low levels on some tumor cell types, e.g. pancreatic ductal adenocarcinoma (Panc89) and fibrosarcoma (HT1080) cell lines." (PMID 24130797, 2013).
brain tumor (5 papers, 2005 to 2021). "Previous studies have found that the inhibition of ADAM17 activity reduces hypoxia-induced brain tumor cell invasion." (PMID 34746310, 2021). "In glioma, ADAM17 promoted brain tumor growth, invasion, metastasis, and contribute to stoke-induced neurogenesis." (PMID 34182543, 2021). "Our findings add to a growing literature describing hypoxia-induced activation of ADAM17-dependent proteolytic cleavage of proteins promoting aggressive tumor cell properties like stemness and invasive growth in brain tumors and other cancer forms." (PMID 32205867, 2020). "Our study suggests that Sp1 transcription factor mediates hypoxia-induced ADAM17 expression and proteolytic activity, and contributes to an increase in invasiveness of brain tumor cells under normoxic and hypoxic conditions." (PMID 19772640, 2009). "In addition, ADAM17 facilitates the release of several integrins from the cell surface, and influences the invasive activity of several cells, including brain tumor." (PMID 19772640, 2009).
HIV-1 infection (5 papers, 2016 to 2025). The type species of lentivirus and the etiologic agent of acquired immunodeficiency syndrome (AIDS). "More recently, Nef-induced exosome-associated ADAM17 was found to cause quiescent CD4+ T cells to become permissive to HIV-1 infection, whereas ADAM17 along with TNF-α could activate latent HIV-1 in primary CD4+ T lymphocytes and macrophages." (PMID 33567490, 2021). "More recently, Nef-induced exosome-associated ADAM17 (ADAM metallopeptidase domain 17) had rendered resting CD4+ T cells permissive to HIV-1 infection, whereas ADAM17 along with TNF-α has been known to synergistically activate the latent HIV-1 in primary CD4+ T lymphocytes and macrophages." (PMID 26981123, 2016). "We have identified ADAM17 as a host restriction factor that inhibits HIV-1 infection by blocking Env expression." (PMID 40678214, 2025). "As a putative mechanism, we demonstrated that NK cells increased surface ADAM17 expression via elevated plasma IL-18 levels during HIV-1 infection, which in turn reduced surface CD16 downregulation." (PMID 37669308, 2023). "This indicates that defective CD56-CD16+ NK cells, a distinct NK cell subset during HIV-1 infection, preferentially increase ADAM17." (PMID 37669308, 2023). "This highlights ADAM17’s likely importance as a natural barrier to HIV-1 infection." (PMID 40678214, 2025). "Collectively, these findings demonstrate that Nef’s essential function during HIV-1 infection is to counteract the antiviral activities of SERINC5 and ADAM17." (PMID 40678214, 2025). "As GI254023X distinguished ADAM10 and 17 enzymatic activities, we investigated the effect of their specific inhibition to HIV-1 infection using either GI254023X or TAPI-0, a known ADAM17 inhibitor." (PMID 38572241, 2024). "Finally, the involvement of multiple ADAMs is consistent with our observation that single specificity ADAM inhibitors alone, such as potent ADAM17 inhibitor 14mb or ADAM10 inhibitor GI254023X, were less effective than broad specificity inhibitor BB-94 in suppressing HIV-1 infection." (PMID 38572241, 2024).
injury (5 papers, 2014 to 2026). Damage inflicted on the body as the direct or indirect result of an external force, with or without disruption of structural continuity. "The broad biological impact of liver disease-related increase in ADAM17 expression and activity could therefore make inhibition of ADAM17 activity a potential novel target for treating both cholestasis associated liver injury and sickness behavior development." (PMID 35095853, 2021). "In our study, we observed an amelioration of both BDL-associated liver injury and sickness behavior development with DPC 333-mediated ADAM17 inhibition, suggesting that in the setting of cholestatic liver injury, ADAM17 plays a more proinflammatory role." (PMID 35095853, 2021). "These ADAM17-mediated protective effects were observed in experimental in vitro endotoxin-induced liver injury, and in vivo ischemia/reperfusion injury in rats." (PMID 35095853, 2021). "We conclude that ADAM17 is a putative target to develop new therapeutic tools for the treatment of traumatic brain injury." (PMID 30154402, 2018).
ischemia (5 papers, 2012 to 2025). A hypoperfusion of the BLOOD through an organ or tissue caused by a PATHOLOGIC CONSTRICTION or obstruction of its BLOOD VESSELS, or an absence of BLOOD CIRCULATION. "Our data showed that 40 min of ischemia followed by 6 h of reperfusion caused an increase in enzymatic activity of ADAM17." (PMID 32751103, 2020). "Consequently, strategies that inhibit ADAM17-mediated shedding are more relevant for acute ischemia than strategies targeting CD47." (PMID 41590849, 2025). "Thus, ADAM17 KD during IR injury can be beneficial for preventing the consequences of ischemia in retinal tissue, which is in line with the positive influence on RB tumorigenicity seen after ADAM17 KD in retinoblastoma." (PMID 36293469, 2022). "To verify whether ADAM17 is upregulated in retinal IR model, we measured expression and enzymatic activity of this sheddase in C57Bl/6J mice subjected to ischemia followed by different periods of reperfusion." (PMID 32751103, 2020). "Finally, our data suggest that interventions directed at regulating ADAM17 activity can be beneficial for preventing and/or alleviating the consequences of ischemia in retinal tissue." (PMID 32751103, 2020). "In addition, ADAM-17 enhances shedding of tumor necrosis factor (TNF) after ischemia and an ADAM-17 antagonist reduces infarct size after transient middle cerebral artery occlusion." (PMID 22420304, 2012).
lung disease (5 papers, 2018 to 2025). "Our study provides new insights into the regulatory role of the SIRT1/miR-34a-5p/ADAM17 axis in HIV-associated lung disease, particularly in impaired mucociliary clearance (MCC) and inflammation." (PMID 39682757, 2024). "So far, as already cited above, STAT3, controlled by the EGFR/ADAM17 axis, is a modifier of CF lung disease." (PMID 29540993, 2018). "We verified that ADAM17 is elevated in fibrotic lung disease from three perspectives: clinical patients and in vitro and in vivo studies; and our in vivo and in vitro studies provide the specific mechanisms by which ADAM17 activates PF." (PMID 40077919, 2025). "However, previous in vivo experiments pointed towards a generally pro-inflammatory function of ADAM17 in lung disease." (PMID 35892600, 2022). "Another prominent ADAM17 substrate involved in lung disease is the IL-6 coreceptor IL-6R." (PMID 29540993, 2018).
male infertility (5 papers, 2013 to 2024). The inability of the male to effect fertilization of an ovum after a specified period of unprotected intercourse. "In total, 210 ligands were selected for this research and targeted against sex hormone-binding globulin (SHBG), ADAM17, and DNase I as receptor proteins to manage male infertility due to the involvement of these proteins in male infertility events." (PMID 38067423, 2023). "This suggested the potential of natural bioactive compounds as leading candidates for targeting the ADAM17 protein to cure male infertility." (PMID 38067423, 2023). "Molecular docking simulations revealed the binding affinities and specific interactions between acanthoic acid and proteins related to male infertility, including SHBG, ADAM17, and DNase I, with binding affinity values of −10.2, −6.8, and −5.8 kcal/mol, respectively." (PMID 39057081, 2024). "Gossypol-induced male infertility markedly and significantly increased the levels of testicular TBARS, NO, TNF-α, ADAM-17, and interleukins (IL-1β, IL-6, and IL-18) while significantly decreasing the levels of both TIMP-3 and IL-12 compared with those of the control group." (PMID 29849861, 2018).
metabolic syndrome (5 papers, 2021 to 2024). A cluster of metabolic risk factors for CARDIOVASCULAR DISEASES and TYPE 2 DIABETES MELLITUS. "This is confirmed by previous studies on the role of ADAM17 in the development of metabolic syndrome, inflammation and CVD." (PMID 36286024, 2022). "Studies involving up-regulation of this metalloproteinase have been instrumental in highlighting that ADAM17 plays a major role in hepatosteatosis and liver inflammation, ultimately contributing to the development of metabolic syndrome." (PMID 33904577, 2021). "In this review, we focus specifically on the role that the metalloproteinase, A Disintegrin and Metalloproteinase 17 [ADAM17] plays in the development and progression of the metabolic syndrome." (PMID 33904577, 2021). "It is interesting to note that glucose is also a stimulus for promoting expression of ADAM17 which contributes to the metabolic syndrome." (PMID 33904577, 2021). "It is vital to further understand the mechanistic role that ADAM17 plays in the metabolic syndrome." (PMID 33904577, 2021). "After considering our previous metabolic studies with regards to ADAM19 and ADAM28 and the fact that ADAM17 plays a multitude of roles in the pathogenesis of many diseases, it is vital to further understand the role ADAM17 plays in promoting features of the metabolic syndrome." (PMID 33904577, 2021). "Here, we focus specifically on the role of the metalloproteinase A Disintegrin and Metalloproteinase 17 [ADAM17] and how it may impact the metabolic syndrome." (PMID 33904577, 2021). "In this review, we aim to highlight the impact of ADAM17 on the progression of Metabolic Syndrome." (PMID 33904577, 2021). "It is highly likely that ADAM17, ADAM19 and ADAM28 work in concert to promote the metabolic syndrome." (PMID 33904577, 2021).
Sjögren’s syndrome (5 papers, 2022 to 2024). "Our data were in agreement with the findings of Lisi and co-investigators, and they demonstrated that GRO-α/CXCR2 system and ADAM17 correlated expression in sjögren’s syndrome." (PMID 39305454, 2024). "Furthermore, abnormal expression of the ADAM17/AREG axis has been demonstrated in salivary gland epithelial cells (SGECs) in patients with Sjögren’s syndrome." (PMID 39768182, 2024). "However, a more recent study suggested that miR-146a-5p promotes Th17 cell differentiation by targeting the metalloprotease ADAM17 in the primary Sjögren’s syndrome." (PMID 35370692, 2022). "The activation of the ADAM17/AREG/EGFR/ERK1/2 pathway leads to an increased release of pro-inflammatory cytokines in the salivary glands, augmenting the inflammatory status that characterizes the autoimmune rheumatic disease Sjögren’s syndrome (SS)." (PMID 39768182, 2024).
type 1 diabetes (5 papers, 2021 to 2025). "In another study, a mouse model of type 1 diabetes was used to examine the role of endothelial ADAM17 (eADAM17) and proximal tubular ADAM17 (tADAM17) deficiencies in the regulation of the renin–angiotensin system (RAS), renal inflammation, and fibrosis." (PMID 40224489, 2025). "ADAM17 expression and activity are increased in the kidney cortex of OVE26 mice with type 1 diabetes and in renal cells exposed to high glucose concentrations, and high ADAM17 mRNA staining was observed in the glomerular parietal epithelium and podocytes from several renal diseases, including DN." (PMID 33634991, 2021).
chronic obstructive pulmonary disease (4 papers, 2016 to 2021). A chronic and progressive lung disorder characterized by the loss of elasticity of the bronchial tree and the air sacs, destruction of the air sacs wall, thickening of the bronchial wall, and mucous accumulation in the bronchial tree. "In addition, ADAM17 plays a crucial role in activating pathological airway remodeling in lung diseases, including asthma, chronic obstructive pulmonary disease (COPD) and cystic fibrosis." (PMID 33579029, 2021). "More specifically, in a review by Stolarczyke and Scholte examining chronic obstructive pulmonary disease and cystic fibrosis, extensive evidence was found linking hyperactivity of the EGFR/ADAM17 signaling axis to ADAM17-cleavage of amphiregulin, an EGFR ligand." (PMID 34745017, 2021). "Aberrant activity of a disintegrin and metalloprotease 17 (ADAM17), also known as TACE, and epidermal growth factor receptor (EGFR) has been suggested to contribute to chronic obstructive pulmonary disease (COPD) development and progression." (PMID 27561911, 2016).
E. coli infection (4 papers, 2017 to 2020). "E. coli infection resulted in the upregulation of the genes encoding proteases, which participate in the degradation of ECM, namely, ADAM10 (logFC of 2.62), ADAM17 (logFC of 8.75), MMP9 and MMP14 (both with a logFC of 2.58), CAPN7 and CAST (both with logFC of 2.20)." (PMID 32234079, 2020). "During E. coli infection, conditional ADAM17 knockout mice lacking ADAM17 in all leukocytes demonstrated a survival advantage and a marked reduction in bacterial levels at the site of infection." (PMID 28487846, 2017).
esophageal squamous cell carcinoma (4 papers, 2020 to 2024). Esophageal squamous cell carcinoma (ESCC) is a type of esophageal carcinoma (EC) that can affect any part of the esophagus, but is usually located in the upper or middle third. "POSTN is mainly expressed by CAFs and its expression induces the expression of a disintegrin and metalloproteinase 17 (ADAM17) in esophageal squamous cell carcinoma cells resulting in tumor progression." (PMID 39695086, 2024). "For instance, ADAM17 protein was highly expressed in esophageal squamous cell carcinoma (ESCC) and promoted the development, invasion and metastasis of ESCC." (PMID 33100908, 2020).
head and neck squamous cell carcinoma (4 papers, 2011 to 2020). A squamous cell carcinoma that arises from any of the following anatomic sites: lip and oral cavity, nasal cavity, paranasal sinuses, pharynx, larynx, and salivary glands. "Deregulation of ADAM17 has previously been implicated in head and neck squamous cell carcinoma (HNSCC), with up-regulation of ADAM17, as well as increased sheddase activity, correlating with tumour aggressiveness, rate of growth and prognosis in this and other cancers." (PMID 32236893, 2020). "MiR-145 targets the SOX9/ADAM17 axis in the head and neck squamous cell carcinoma." (PMID 26657507, 2016).
influenza (4 papers, 2013 to 2024). An acute viral infection of the respiratory tract, occurring in isolated cases, in epidemics, or in pandemics; it is caused by serologically different strains of viruses (influenzaviruses) designated A, B, and C, has a 3-day incubation period, and usually lasts for 3 to 10 days. "In contrast, others have reported effector CD8 T cell activation during influenza infection resulting in ADAM17-mediated TNFRII cleavage and release from the cell surface membrane." (PMID 35095853, 2021). "Importantly, the ability to protect from an otherwise lethal influenza infection was not impaired by ADAM17-deficiency, as adoptive transfer of virus-specific ADAM17−/− CD8+ T cells into mice infected with a lethal dose of influenza virus provided complete protection against death." (PMID 24223177, 2013). "Taken together, these results indicate that ADAM17 activity on transferred CD8+ T cells is critical for the initiation of severe and lethal lung injury in a transgenic mouse model of influenza pneumonia." (PMID 24223177, 2013). "CD8+ T-cell-specific inhibition of ADAM17-mediated processing of TNF-α resulted in decreased chemokine production by alveolar epithelial cells and reduced cellular infiltration of the airways, attenuating tissue injury and mortality in a transgenic mouse model of influenza pneumonia." (PMID 24223177, 2013). "Furthermore, we found that CD8+ T-cell-specific inhibition of TNF-α processing did not impair host protection against influenza virus as influenza-specific ADAM17−/− CD8+ T cells were able to provide complete protection against an otherwise lethal viral challenge." (PMID 24223177, 2013).
metastatic tumors (4 papers, 2012 to 2023). "Our data showed these ADAM17 mutations were present in six separate foci of metastatic tumors in two patients with each mutation from three foci in each patient." (PMID 30627328, 2018). "They found that ADAM8 was expressed significantly higher in metastatic tumors as well as identifying several proteinases of the ADAM-family (ADAM9, ADAM17, ADAM28, ADAMTS1, ADAMTS8 and ADAMTS15) -including ADAM8- which are HNSCC associated." (PMID 22369429, 2012).